GPR17 (G protein-coupled receptor 17)
Diseases named in the same sentence as GPR17 in open-access papers (continued):
Sharing a sentence is not in itself a finding about the gene and the disease.
myocardial infarction (1 paper, 2014). Gross necrosis of the myocardium, as a result of interruption of the blood supply to the area, as in coronary thrombosis. "In the present report, the expression of GPR17 was investigated in mice before and at early stages after myocardial infarction by using immunofluorescence, flow cytometry and RT-PCR." (PMID 24909956, 2014).
periventricular leukomalacia (1 paper, 2021). Periventricular leukomalacia (PVL) is a brain injury disorder characterized by the death of the white matter of the brain due to softening of the brain tissue. "The present study aimed to investigate the function of GPR17 in the white matter of periventricular leukomalacia (PVL) neonatal rats." (PMID 34569901, 2021).
tumor (11 papers, 2009 to 2025). "The promotive effect of C1q on tumor cell DNA methylation was also restricted in the GPR17 knockdown condition." (PMID 40171991, 2025). "Mechanistically, C1q activates the Phosphatidylinositol‐3‐kinase (PI3K)/AKT pathway through interacting with GPR17, a member of the G protein‐coupled receptor family, thereby inducing DNA hypermethylation of tumor cells to promote tumor development." (PMID 40171991, 2025). "By comparing differentially expressed gene (DEG) profiles of tumor cells to those of the other cell types in the tumors, we discovered Neu4 and Gpr17 as tumor-specific markers." (PMID 41497446, 2025). "Tumor microenvironment (TME) soluble mediator (Ccl2, Ccl3, Ccl4, Ccl5) and tumor cell marker (NeuN, Gpr17) RNA expression was quantitated by qRT-PCR." (PMID 41497446, 2025). "The discovery of astrocyte-like and oligodendrocyte-like tumoral cells prompted us to analyze the expression of the G protein-coupled receptor GPR17." (PMID 33925547, 2021). "In vivo activation of GPR17 by GA-T0 reduces the tumor volume, uncovering the potential of GA-T0–GPR17 as a targeted therapy for GBM treatment." (PMID 34359676, 2021). "However, all treatments that reduced Nf1-OPG proliferation also exhibited decreased Neu4 and Gpr17 expression, suggesting similar effects of the various treatments on tumor cell content." (PMID 41497446, 2025). "Our study revealed that C1q binds to GPR17 to induce DNA hypermethylation of tumor cells." (PMID 40171991, 2025). "Furthermore, hematoxylin eosin (H&E) staining confirmed the suppressed tumor formation by GPR17 overexpression." (PMID 34120140, 2021). "We have previously shown that GPR17 regulated transcription, but whether and how GPR17 was involved in gene regulation in tumor cells remained unknown." (PMID 34120140, 2021). "Thus, GPR17-mediated signaling activation promotes the inhibition of GBM tumor growth and proliferation." (PMID 34359676, 2021). "In the TME of NPC, C1q secreted by C1q+ TAMs interacted with GPR17 to activate PI3K/AKT signaling through strengthening GPR17 coupling PI3K and increasing calcium levels in tumor cells." (PMID 40171991, 2025). "The limited insight into GPR17 signaling in GBM and its tumor microenvironment prompted us to investigate the mechanism of GPR17 signaling activation, the downstream effects, its role in cell death and therapeutic applications in GBM treatment." (PMID 34359676, 2021). "In the tumor samples from GBM patients, the expression of GPR17 was about 32% of the level in LGG samples." (PMID 34120140, 2021). "A group of 4 genes (ARX, GPR17, LHX2 and CXCL14) well stratified LGGs between infratentorial and supratentorial tumours." (PMID 23947815, 2013). "The epigenetic reactivation of TKTL1, H19, MAGEA2, MAGEA3/6, MAGEA4, MAGEA11, GPR17, GRIN1, and C19ORF28, genes located at diverse chromosomal loci, occurs simultaneously in individual primary tumors from multiple tumor types." (PMID 19305507, 2009). "Specifically, the level 3 classifier shows strong correlations among genes like KRT5, S100A7, KRT16, S100P, and LY6D, while the level 6 classifier exhibits similar patterns with GPR17, RGR, and NPPA, highlighting the complex interplay of genes in tumor subtype classification." (PMID 40802546, 2025). "Neu4 and Gpr17 were expressed in >45% of the cells in the tumor cell cluster, <2% of the cells in the non-tumor cell clusters, with an average log2 fold change >4.5." (PMID 41497446, 2025). "Additional in vivo data are also distinct, showing a reduction in tumor volume without affecting the local cellular environment, suggesting the potential role of GPR17 as a targeted therapy against GBM." (PMID 34359676, 2021). "However, our data revealed that GPR17 signaling activation using GA-T0, observed to arrest cell cycle, induces apoptosis and show a cytotoxic effect against GBM cells, as well as in patient-derived cell lines, with significant tumor cytotoxicity in in vivo PDX animal models." (PMID 34359676, 2021).
neurodegenerative disease (6 papers, 2015 to 2022). A disorder of the central nervous system characterized by gradual and progressive loss of neural tissue and neurologic function. "In a word, our results have profound implications for understanding the structural basis underlying mechanism of GPR17 and may provide rational, structure‐based, approaches for ligand screening on GPR17 for the treatment of neurodegenerative diseases." (PMID 36105372, 2022). "Given these important roles, GPR17 has become a promising target for pharmacological intervention in the neurodegenerative diseases, ischemic damage, and energy metabolism dysregulation." (PMID 36105372, 2022). "The G protein-coupled receptor 17 (GPR17) has recently been proposed as an interesting pharmacological target in neuroinflammatory and neurodegenerative diseases." (PMID 34769111, 2021). "Besides leukotrienes, other ligands and agonists for GPR17 have been described, which might well contribute to the activation of the receptor in ageing and in neurodegenerative diseases." (PMID 26506265, 2015). "Also, the cryo‐EM structure of GPR17 we reported reveals the potential ligand‐binding pocket, which may benefit the further research on the leading compound screening to overcome the great challenge of neurodegenerative diseases." (PMID 36105372, 2022). "Based on our previous data on alterations of GPR17 expression in MS pathogenesis and remyelination failure, we suggest that these functional and mechanistic insights may inspire new pharmacological and therapeutic approaches for the cure of neurodegenerative diseases." (PMID 35954217, 2022). "Thus, we believe that targeting GPR17 with new selective compounds in combination with the already available immunosuppressive/anti-inflammatory drugs could represent a promising reparative strategy for MS and other neurodegenerative diseases characterized by demyelination." (PMID 32320409, 2020).
cancer (2 papers, 2021 to 2022). A tumor composed of atypical neoplastic, often pleomorphic cells that invade other tissues. "We investigated GPR17 expression from publicly available RNAseq gene expression cancer datasets using the GEPIA portal." (PMID 34359676, 2021).
metabolic disease (2 papers, 2021 to 2024). A congenital disorder (due to inherited enzyme abnormality) or acquired (due to failure of a metabolically important organ) disorder resulting from an abnormal metabolic process. "Our previous studies demonstrated the physiological role of hypothalamic Gpr17 in maintaining metabolic homeostasis in rodents and the potential implications of human GPR17 genetic variants in metabolic diseases." (PMID 39858405, 2024). "Here, we sought to experimentally characterize the expression, localization, and functional signaling consequences of the naturally occurring human GPR17 genetic variants observed in the metabolic disease cohorts." (PMID 34144038, 2021). "We report the identification of naturally occurring missense variants of GPR17 and the functional signaling profiles of nine variants identified in individuals with metabolic disease." (PMID 34144038, 2021). "Collectively, further investigation will be necessary to fully evaluate the contribution of the rare GPR17 variant alleles to the clinical phenotypes that accompany metabolic diseases." (PMID 34144038, 2021). "Several human GPR17 variants identified in individuals with metabolic diseases had altered downstream signaling." (PMID 34144038, 2021). "Sequence analysis for the GPR17 coding sequences of individuals from control and metabolic disease cohorts identified 18 nonsynonymous GPR17 variants." (PMID 34144038, 2021). "However, links between human GPR17 genetic variants, downstream cellular signaling, and metabolic diseases have yet to be reported." (PMID 34144038, 2021). "More comprehensive evaluation of GPR17 variants including those identified from individuals in the control cohorts and in both the control and metabolic disease cohorts is expected to add to our understanding of the link between GPR17 signaling function and metabolic diseases." (PMID 34144038, 2021). "The identification and functional profiling of naturally occurring human GPR17 variants from individuals with metabolic diseases revealed receptor variants with diverse signaling profiles, including differential signaling perturbations that resulted in GPCR signaling bias." (PMID 34144038, 2021). "Studies that utilize a larger sample size and investigate the allelic expression profile and balance of variant and wild-type allele expression in a given individual and tissue type are expected to provide more insight into the link between GPR17 variants and metabolic diseases in humans." (PMID 34144038, 2021). "Our study revealed underlying mechanisms for GPR17 regulation of GLP-1 secretion and provided insight to guide novel targeting strategies to maximize GLP-1 secretion as a treatment for metabolic diseases." (PMID 39858405, 2024). "Human GPR17 gene sequences were obtained and analyzed for 4054 samples from control and metabolic disease cohorts from the UK10K project." (PMID 34144038, 2021). "Our findings provide a framework for structure–function relationship studies of GPR17 signaling and metabolic disease." (PMID 34144038, 2021). "Such evidence is primarily drawn from mouse knockout studies and suggests GPR17 as a potential novel therapeutic target for the treatment of metabolic diseases." (PMID 34144038, 2021). "Targeting GPR17 to elevate GLP-1 secretion may represent another potential therapeutic approach for the treatment of metabolic diseases." (PMID 39858405, 2024).
nervous system diseases (2 papers, 2021 to 2022). "Regarding the factors leading to GPR17 dysregulation in neurological disorders, increasing evidence in different models of demyelination suggests that GPR17 overexpression is sustained by pro-inflammatory cytokines accumulating close to inflamed lesions." (PMID 33925469, 2021).
neurodevelopmental disorder (1 paper, 2023). A behavioral and cognitive disorder with onset during the developmental period that involves impaired or aberrant development of intellectual, motor, or social functions. "Recent evidence has highlighted a role for the G protein-coupled P2Y-like receptor GPR17 in neurodevelopmental disorders of genetic origin." (PMID 37238724, 2023). "In conclusion, these findings uncover a critical role of GPR17 in the OL defects that are observed in neurodevelopmental disorders and suggest that modulation of its signaling might be a potential therapeutic approach for treating these conditions." (PMID 37238724, 2023).
GPR17 also shares sentences with these, for which no sentence is quoted: Cerebral ischemia (4 papers); type 2 diabetes (3); Alzheimer disease (1); brain disease (1); cardiovascular diseases (1); Cerebral degeneration (1); demyelination (1); Down syndrome (1); Hypercholesterolemia (1); memory impairment (1); nasopharyngeal carcinoma (1); ocular hypertension (1); oligodendroglioma (1); pilocytic astrocytoma (1); polyp (1); psychosis (1); spina bifida (1).